ENSG00000220986
Gene: Small nucleolar RNA gene on chromosome 5 (69,160,806 to 69,160,939, forward strand). Ensembl gene ENSG00000220986.
Gene Ontology:
Biological process: RNA processing
Cellular component: nucleolus
Homologues: Orthologues: mouse Gm22711 (72% identical), mouse Gm23786 (62% identical), mouse Gm26047 (55% identical). Paralogues in human: SNORA50A (57% identical).